BMP2 (bone morphogenetic protein 2)
Diseases named in the same sentence as BMP2 in open-access papers (continued):
Sharing a sentence is not in itself a finding about the gene and the disease.
cervical carcinoma (2 papers, 2016 to 2025). A carcinoma arising from either the exocervical squamous epithelium or the endocervical glandular epithelium. "Endometrial CSCs are supported by pathways involving TGFβ, BMP2, and Netrin-4/c-Myc signaling, while in cervical cancer, VEGF, IGF-1, Gremlin-1, and TGFβ-mediated circuits enhance stem-like phenotypes and drug resistance." (PMID 41373619, 2025).
cleft palate (2 papers, 2021 to 2022). Cleft palate is a fissure type embryopathy that affects the soft and hard palate to varying degrees. "In humans, BMP2 recombinant protein can regenerate mandibular continuity and cleft palate defects." (PMID 35634164, 2022).
cognitive deficits (2 papers, 2019 to 2021). "Hippocampal neuronal apoptosis through an upregulated BMP2 (bone morphogenetic proteins) attenuation induces cognitive deficits in As poisoning." (PMID 34621902, 2021). "As induces hippocampal neuronal apoptosis through an up regulated none morphogenic protein 2 (BMP2), Smad dependent attenuation of BDNF TrkB pathway resulting cognitive impairments." (PMID 31199848, 2019).
congenital heart defects (2 papers, 2019 to 2023). "BMP2 variants predicted to result in haploinsufficiency are associated with short stature, craniofacial gestalt, skeletal anomalies, and congenital heart disease." (PMID 30735122, 2019). "Our study is the first according to our knowledge that examined all exons of the BMP2 and BMP4 genes to determine possible molecular defects such as insertions/deletions or single nucleotide polymorphisms (SNPs) that are possibly associated with the risk of congenital heart disease." (PMID 37627976, 2023). "To provide some insight into the role of BMP-2 and -4 in ASD, VSD and other complex congenital defects, in the present study we examined 52 cases of congenital heart defects (ASD, VSD and complex defects) for possible molecular defects in the BMP2 and BMP4 genes." (PMID 37627976, 2023). "Moreover, when each of the congenital heart defect subgroups ASD and VSD was compared to the normal hearts, similar fold expression values were found regarding BMP2 mRNA (p = 0.72, p = 0.33, respectively, t-test) and BMP4 mRNA (p = 1.00, p = 0.99, respectively, t-test)." (PMID 37627976, 2023). "Sanger sequencing of all coding exons of BMP2 and BMP4 genes was performed on all 52 patients with a congenital heart disease, as well as on 100 blood donors with non-CHD hearts." (PMID 37627976, 2023).
diabetic cardiomyopathy (2 papers, 2023). Diabetic cardiomyopathy is a disorder of the heart muscle in people with diabetes. "Diabetic cardiomyopathy also resulted in increased expression of Tbx20 (4.4 ± 0.5-fold) and Bmp2 (2.9 ± 0.5-fold) as compared with control group." (PMID 36805334, 2023). "BMPs (BMP2, BMP4, and BMP7) elicit anti-atherogenic and anti-inflammatory effects, while reducing LV remodeling and preserving cardiac function in diabetic cardiomyopathy." (PMID 37240345, 2023).
endometrial cancer (2 papers, 2022 to 2023). Primary or metastatic malignant neoplasm involving the endometrium (mucous membrane that lines the endometrial cavity). "High expression of BMP2 and BMP7 mRNA is associated with poorer survival in patients with endometrial cancer, albeit not significantly for BMP2." (PMID 35693928, 2022).
enthesitis (2 papers, 2016 to 2023). Inflammation at the site of insertion of ligaments, tendons, and other fibrous structures into bone. "BMP-2, 6, and 7 are probably involved in different stages of the enthesitis process and MSC differentiation into osteoblasts." (PMID 37834372, 2023). "Expressions of further BMP family members (BMP-2, BMP-4, and BMP-7) were reportedly increased at sites of enthesitis in a mouse model of SpA and at the Achilles tendon in biopsies of early-stage humans enthesopathy." (PMID 27314037, 2016).
glomerulosclerosis (2 papers, 2022 to 2023). A hardening of the kidney glomerulus caused by scarring of the blood vessels. "Notably, the BMP2/4 signaling pathways identified in DN mesangial cell interactions contribute to glomerulosclerosis and tubulointerstitial fibrosis, particularly in DN." (PMID 36627643, 2023).
hypothyroidism (2 papers, 2025). Abnormally low levels of thyroid hormone. "Additionally, hypothyroidism led to reduced uterine gene expression of LIF, BMP2, WNT4, and HAND2." (PMID 39859259, 2025).
interstitial nephritis (2 papers, 2014 to 2020). Inflammation of the renal tubules and supporting tissues of the kidney. "Twenty genes were randomly selected including alkaliphilic serine protease, two putative cuticle protein CPH45, tubulointerstitial nephritis antigen precursor, serine protease precursor, Bmp-2 protein, fungal protease inhibitor F precursor and putative serotonin receptor and so on." (PMID 24801594, 2014). "Additionally, in a model of interstitial nephritis, induced inactivation of the ALK3 receptor (a high-affinity receptor for BMP2 and BMP4) sensitizes proximal tubule cells to injury and promotes fibrosis." (PMID 33328501, 2020).
invasive breast carcinoma (2 papers, 2017 to 2019). A carcinoma that infiltrates the breast parenchyma. "We found that expressions of BMP-2 and CD44 were significantly upregulated, whereas expressions of RB1 and CDH1 (E-cadherin) were significantly downregulated in invasive breast cancer." (PMID 28725489, 2017).
kidney stone (2 papers, 2022). "It has been previously demonstrated that IL-6 and MCP-1 indicated a close relationship between inflammation and kidney stones, while our previous research has confirmed that osteogenic transformation-related proteins BMP2 and OPN played important roles in stone formation." (PMID 35124708, 2022).
knee osteoarthritis (2 papers, 2022 to 2024). "Here, we found that Dlx5, SP7, and BMP-2 were all increased in papain-induced knee osteoarthritis, and upregulation of SP7 and BMP-2 were partly dependent on Dlx5." (PMID 35280506, 2022).
liposarcoma (2 papers, 2016 to 2021). A usually painless malignant tumor that arises from adipose tissue. "Herein, we utilise large publicly available datasets from The Cancer Genome Atlas (TCGA) and Protein Atlas to define a novel role for BMP2 in the progression of dedifferentiated liposarcomas." (PMID 27114889, 2016). "In summary, we present here evidence that high expression of BMP2 leads to extracellular matrix remodelling and tumour progression in dedifferentiated liposarcomas, only within the context of high BMPR1B expression." (PMID 27114889, 2016). "Through further annotation of the TCGA sarcoma dataset, we localise this effect to dedifferentiated liposarcomas but find overall BMP2/BMP receptor expression is equal across subsets." (PMID 27114889, 2016). "For the first time, we identify high BMP2 expression within the context of high BMPR1A expression as a biomarker of disease relapse in dedifferentiated liposarcomas." (PMID 27114889, 2016). "Thus, it appears that the detrimental effects of BMPR1A biased BMP2 expression are confined to the context of soft tissue sarcomas and in particular dedifferentiated liposarcomas." (PMID 27114889, 2016). "Further to linking BMPR1A-biased BMP2 expression to reduced disease free survival, we report a detailed differential expression analysis in both the sarcoma dataset as a whole and dedifferentiated liposarcomas." (PMID 27114889, 2016). "Interestingly, we find that the prognostic value of BMPR1A biased BMP2 expression in sarcomas is localised to dedifferentiated liposarcomas and not leiomyosarcomas." (PMID 27114889, 2016).
long bone fracture (2 papers, 2011 to 2016). "A total of fifteen SNPs within four genes of the Bone Morphogenetic Protein (BMP) pathway (BMP-2, BMP-7, NOGGIN and SMAD6) were examined, in 109 randomly selected patients with long bone fractures as a result of motor vehicle accident, fall or direct blow." (PMID 21310029, 2011). "Novel and sensitive assays for the quantification of BMP7-aAB and BMP2-aAB were established and used to analyze serum samples from healthy controls (n = 100 men, n = 100 women) and patients with long bone fracture (n = 265) treated or not with rhBMP7." (PMID 27617228, 2016).
malnutrition (2 papers, 2013 to 2020). Inadequate nutrition resulting from poor diet, malabsorption, or abnormal nutrient distribution. "Malnutrition is prevalent in hemodialysis patients and is associated with arterial calcification and the expressions of BMP2 and MGP in calcified radial arteries." (PMID 23506394, 2013). "However, whether malnutrition participates in the process of arterial calcification and associates with the expressions of BMP2 and MGP are not well understood." (PMID 23506394, 2013). "For the first time in hemodialysis patients to our knowledge, we demonstrated that malnutrition (a high MQSGA score and a low level of serum albumin) was closely associated with arterial calcification and the expressions of BMP2 and MGP." (PMID 23506394, 2013).
microphthalmia (2 papers, 2010 to 2018). Congenital or developmental anomaly in which the eyeballs are abnormally small. "Additionally, compound heterozygous mice for Bmp4 and Bmp2 present with microphthalmia and retinal degeneration." (PMID 29738572, 2018).
Mycoplasma infection (2 papers, 2020 to 2022). "Additionally, it was demonstrated that BMP2 stimulated proliferation of BEAS-2B cells transformed by chronic Mycoplasma infection, indicating the profound effects of Mycoplasma infection on BMP2-regulated pathways, including the ones involved in cell proliferation, differentiation, and apoptosis." (PMID 32899663, 2020).
Myocardial fibrosis (2 papers, 2012 to 2019). "SPARC-related modular calcium binding 1 (SMOC1) silencing can suppress myocardial fibrosis of mouse myocardial fibroblasts via regulation of the bone morphogenetic protein 2 (BMP2)/Smad signaling pathway." (PMID 32038243, 2019). "To prove whether BMP-2 inhibition promoted TGF-β1-mediated fibrotic signalling pathway, we examined TGF-β1-induced activation of PKC-δ and Smad3, two important signal molecules that induced myocardial fibrosis, after knocking down BMP-2 in cardiomyocytes." (PMID 22283839, 2012).
non-alcoholic fatty liver disease (2 papers, 2022 to 2024). "Increased gene expression of BMP2 has been reported in human osteoblasts treated with cadmium and in patients with non-alcoholic fatty liver disease (NAFLD)." (PMID 38468450, 2024).
pericardial effusion (2 papers, 2020 to 2023). Fluid collection within the pericardial sac, usually due to inflammation. "Altogether, our data demonstrate that BMP2 GT causes inflammatory changes and pericardial effusion in ischemic myocardium, which does not support its therapeutic use in chronic CAD." (PMID 38028463, 2023). "However, BMP2 gene transfer induced pericardial effusion (AdBMP2: 9.41 ± 3.17 mm; AdLacZ: 3.07 ± 1.33 mm) that was measured by echocardiography." (PMID 38028463, 2023). "Taken together, our data demonstrate that BMP2 GT is unsuitable for inducing beneficial effects in adult myocardium after chronic ischemia and that BMP2 transgene induces pericardial effusion and inflammatory responses, which prevent its use in treating chronic CAD." (PMID 38028463, 2023). "Our results demonstrate that BMP2 gene transfer causes inflammatory changes and pericardial effusion in the adult ischemic myocardium, which thus does not support its therapeutic use in chronic CAD." (PMID 38028463, 2023). "BMP2 plays a vital role in modulating AV canal morphogenesis, as mice with BMP2 specifically inactivated in AV myocardium showed abnormal AV canal morphology at 9.5 days post coitum (dpc) and pericardial effusion and growth retardation at 10.5 dpc." (PMID 32373613, 2020).
preeclampsia (2 papers, 2021). Preeclampsia is a hypertensive disorder of pregnancy that is characterized by new-onset hypertension with proteinuria presenting after 20 weeks of gestation, and depending on mild or severe forms may initially present with severe headache, visual disturbances, and hyperreflexia. "Therefore, we next sought to confirm the dysregulation of placental BMP2 expression in preeclampsia samples." (PMID 34970543, 2021). "A retrospective cohort study was conducted to compare the expression and localization of BMP2 in placentas from EOPE (n = 20) and non-preeclampsia preterm controls (n = 20)." (PMID 34970543, 2021).
radiation pneumonitis (2 papers, 2017 to 2021). Inflammation of the lung due to harmful effects of ionizing or non-ionizing radiation. "For patients who underwent RT, BMP2:rs235756 was shown to predict radiation pneumonitis, which is an important clinical outcome." (PMID 34307117, 2021).
rheumatoid arthritis (2 papers, 2017 to 2020). A chronic, systemic autoimmune disorder characterized by inflammation in the synovial membranes and articular surfaces. "In patients with rheumatoid arthritis, stimulation with IL-1β induced BMP-2 and BMP-6, but not BMP-4, BMP-5, or BMP-7 in fibroblast-like synoviocytes." (PMID 32290085, 2020).
sarcoma (2 papers, 2016 to 2022). A usually aggressive malignant neoplasm of the soft tissue or bone. "To discount prognostic influences of BMPR1A, BMPR1B or BMP2 expression individually, we constructed Kaplan-Myer curves for the entire sarcoma dataset and compared patients with the highest and lowest 10% expression of BMPR1A, BMPR1B, BMPR2, BMP2 and BMP7." (PMID 27114889, 2016). "As the largest differences in receptor expression patterns were observed in sarcoma cell lines and normal soft tissues, we elected to focus our analysis on BMP2 in the soft tissue sarcoma TCGA dataset." (PMID 27114889, 2016). "Similarly, we find that sarcoma patients with BMPR1A biased BMP2 expression have significantly reduced disease free survival." (PMID 27114889, 2016). "We chose three potential target proteins such as TFGF-Beta, BMP2, and FGFR to validate their differential expressions using selection reaction monitoring (SRM) mass spectrometry methodology using a newly recruited sample set of high-grade sarcoma patients." (PMID 35806417, 2022). "Therefore, we chose three proteins such as BMP2, TGF-Beta, and MMP9 to confirm the expression levels using target proteomic analysis and Western blotting techniques using another newly recruited set of high-grade sarcoma patients (n = 18) of untreated and treated (n = 18) for confirmation analysis." (PMID 35806417, 2022).
small cell lung carcinoma (2 papers, 2022 to 2023). Small cell lung cancer (SCLC) is a highly aggressive malignant neoplasm, accounting for 10-15% of lung cancer cases, characterized byrapid growth, and early metastasis. "Neuron-specific enolase promoted stem cell-like characteristics of small cell lung cancer cells by activating the BMP2/Smad/ID1 pathway." (PMID 37416767, 2023).
spina bifida (2 papers, 2021 to 2022). A congenital neural tube defect in which vertebrae are not fully formed. "Our results further support this evidence as Sox9, Notch1, and BMP2/4 gene expression was upregulated at the time of early astrogliosis in spina bifida, and BMP2/4 expression with S100b and Aldh1l1, an early astrocyte markers." (PMID 35782393, 2022). "These specific genes were also significantly reduced in prenatal neurosphere cultures after BMP2 treatment, indicating the potential role of BMP2 in diminishing myelination during the progression of spina bifida." (PMID 34942894, 2021).
spondylitis (2 papers, 2020). The inflammation of a vertebra. "In addition to the previously observed correlation of BMP-2 levels with the Bath Ankylosing Spondylitis Indexes, we noticed a correlation with OPG and CRP markers." (PMID 33046134, 2020).
teratoma (2 papers, 2017 to 2018). A non-seminomatous germ cell tumor characterized by the presence of various tissues which correspond to the different germinal layers (endoderm, mesoderm, and ectoderm). "Ganciclovir (GCV) treatment induced apoptosis in TDF cells co-expressing HSV-tk and BMP-2, implying that HSV-tk suicide gene can modulate the side-effects of stem cell therapy, e.g., development of uncontrollable teratoma and tumor formation." (PMID 30275449, 2018). "Additionally, we performed the teratoma formation assay using cells dissociated from the DRG explants cultured for 6 days in the presence of LIF/BMP2/FGF2, and found that teratomas were formed by injecting dissociated DRG cells treated with LIF/BMP2/FGF2." (PMID 28373172, 2017).
uremia (2 papers, 2020 to 2023). A clinical syndrome associated with the retention of renal waste products or uremic toxins in the blood. "These toxins, particularly PC, contribute significantly to uremia-associated vascular disease by increasing in THP-1 cells the expression of BMP-2, NF-κB, and key miRNAs associated with the development of atherosclerotic vascular diseases." (PMID 37629118, 2023). "Another marker directly related to the CVD associated with uremia is BMP2." (PMID 32850849, 2020).
alcoholism (1 paper, 2013). "Heterodimeric bone morphogenetic protein-2/7 bears a promising application potential to significantly promote bone regeneration and implant osteointegration for the patients with hypervitaminosis A and alcoholism." (PMID 24205156, 2013).
amelogenesis imperfecta (1 paper, 2017). Amelogenesis imperfecta (AI) represents a group of developmental conditions affecting the structure and clinical appearance of the enamel of all or nearly all the teeth in a more or less equal manner, and which may be associated with morphologic or biochemical changes elsewhere in the body. "Conditional deletion of BMP2 and BMP4 using K14-cre mice (which have keratin-14 promoter-driven cre recombinase) resulted in amelogenesis imperfecta caused by downregulation of the removal of enamel matrix protein during maturation." (PMID 29273814, 2017).
anaplastic oligodendroglioma (1 paper, 2016). A WHO grade III oligodendroglioma with focal or diffuse malignant morphologic features (prominent nuclear pleomorphism, mitoses, and increased cellularity). "Our gene signature also contained proneural genes, BMP2, DCX, IGFBP2, PDPN, and PLAT, which are associated with anaplastic oligodendroglioma harboring 1p/19q co-deletion." (PMID 27323413, 2016).
Anophthalmia (1 paper, 2021). Absence of the globe or eyeball. "Although SOX2 in anophthalmia, persistent hyperplastic primary vitreous in NDP, and micrognathia in BMP2 were detected in this study, up to 60% of cases with underlying genetic causes remained undetermined." (PMID 34367232, 2021).
asthma (1 paper, 2022). "Significant DMPs fall within genes involved in the TFG-β related pathways (e.g. BMP2, FLCN, ING2, PMEPA1, PRDM16, TGFB1I1 and TGFBR3), in line with previous studies that reported an association between these genes and the increased asthma risk." (PMID 35619695, 2022).
astrocytic tumor (1 paper, 2025). A glial tumor of the brain or spinal cord showing astrocytic differentiation. "Figure 2illustrates the promoter methylation status of six genes involved in the TGF-β signaling pathway—SKIL, SMAD1, SMAD3, SMAD4, BMP2, and MAPK1—across astrocytic tumors of increasing malignancy (grades G2, G3, and G4)." (PMID 40869118, 2025).
Atrophy (1 paper, 2015). Any weakening or degeneration, especially through lack of use. "The analyzed osteogenic factors (Bmp2, -3, -4 and -7) showed also a dysregulated expression profile in the atrophy group over time." (PMID 25910190, 2015).
B-cell lymphoma (1 paper, 2012). "Altogether, B-cell lymphoma cell lines had variable sensitivity to BMP-2-, -4- and -6-induced growth inhibition, but they were all resistant to BMP-7." (PMID 23049692, 2012).
benign gingival tumor (1 paper, 2024). "Although few adverse events were identified in the retrospective evaluation, bone mass, and swelling are the major ones after BMP-2’s application in maxillofacial surgery, and a wound dehiscence case was also reported after benign gingival tumor removal." (PMID 39472366, 2024).